FOXQ1 (forkhead box Q1)
Diseases named in the same sentence as FOXQ1 in open-access papers (continued):
Sharing a sentence is not in itself a finding about the gene and the disease.
breast carcinoma (continued). "In contrast to these reports, our study demonstrates that the entire MLL core complex is an essential cofactor for the FOXQ1-activated EMT program and metastatic progression in breast cancer." (PMID 36319643, 2022). "DDR2 expression was also independently correlated with FOXQ1 and SNAI1 across TCGA breast cancer data." (PMID 36713812, 2022). "Also, in contrast to findings in breast cancer we could not observe an association of FOXQ1 with EMT features in CRC." (PMID 23555880, 2013). "It remains to be seen if the proposed mechanism also applies to other types of cancer in which FOXQ1 may act as a tumour suppressor, such as HER2-positive breast cancer, or whether it is specific to melanomas." (PMID 39777582, 2025). "However, in some subtypes of breast cancer, namely HER2-positive and luminal breast cancer, FOXQ1 expression levels are lower compared to healthy tissue and triple-negative breast cancer (TNBC)." (PMID 39777582, 2025). "FOXQ1 directly transcriptionally regulates interleukin (IL)-8, IL-1α, and vascular endothelial growth factor (VEGF) to affect the pathological mechanism of human breast cancer cells." (PMID 41347087, 2025). "Together, these findings support that activation of the FGFR1 signaling mainly upregulates FOXQ1 expression and breast cancer cell proliferation through activating ERK2, but not ERK1, in the FGFR1-MEK-ERK2 signaling pathway." (PMID 36778115, 2023). "Knockdown of FOXQ1 gene expression blocked the FGFR1 signaling-promoted breast cancer cell proliferation and colony formation in culture, and inhibited the FGFR1 signaling-accelerated growth in xenograft tumors derived from breast cancer cells in mice." (PMID 36778115, 2023). "There is no obvious correlation between FOXQ1 and total HuR expression among different breast cancer cell lines, since total HuR is expressed in all breast cancer cell lines tested." (PMID 32332873, 2020). "Similarly, other investigators have also shown that FOXQ1 played a key role in nasopharyngeal carcinoma, targeted by miR-506 and miR-124; likewise, HMGB3 in breast cancer is targeted by miR-205; and MKI67 in hepatocellular carcinoma, targeted by miR-519d." (PMID 27119506, 2016). "FoxQ1 was shown to regulate EMT and function in breast cancer." (PMID 25356753, 2014). "FOXQ1 was upregulated in CRC and in metastatic breast cancer cell lines, and could protect lung, breast and colon cancer cell lines from chemotherapy induced apoptosis and regulate EMT in CRC and breast cancer cell lines." (PMID 23555880, 2013). "FOXQ1 (forkhead box protein Q19) is a nuclear transcription factor involved in mammary epithelial cell differentiation and in epithelial-mesenchymal transition (EMT) in breast cancer cells." (PMID 23213280, 2012). "Because the FOXQ1 gene is a protooncogene 25, 36, 37 that has not been studied in FGFR1-regulated cell growth, we aimed to investigate how FGFR1 signaling upregulates FOXQ1 expression and whether FOXQ1 is responsible for mediating breast cancer cell growth promoted by FGFR1 signaling." (PMID 36778115, 2023).
colorectal cancer (38 papers, 2012 to 2025). A primary or metastatic malignant neoplasm that affects the colon or rectum. "In 2010, Kaneda and colleagues reported that FOXQ1 expression is strongly increased in tissue samples from patients with colorectal cancer (CRC), and that its induction inhibited the apoptosis of CRC cell lines in the presence of chemotherapeutic drugs." (PMID 39777582, 2025). "For example, TAMs have been shown to regulate the IL-6/JAK2/STAT3/miR-506-3p/FoxQ1 axis, which enhances colorectal cancer (CRC) motility and invasion through the induction of EMT and upregulation of CCL2, promoting macrophage recruitment." (PMID 40083697, 2025). "Accordingly, FOXQ1 induction is recognised as an independent prognostic factor for worse overall survival in several types of cancer, including gastric and colorectal cancer." (PMID 39777582, 2025). "The downregulation of miR-506-3p in colorectal cancer cells results in elevated FoxQ1 expression, whereas the upregulation of FoxQ1 enhances the synthesis of the chemokine CCL2, therefore attracting additional macrophages." (PMID 40772228, 2025). "FOXQ1 expression was validated in two large screening cohorts (n=550) and an independent clinical validation cohort (n=134), demonstrating that high FOXQ1 expression is an independent prognostic factor in colorectal cancer patients." (PMID 41347087, 2025). "FOXQ1 levels are dramatically increased in various types of cancer, including colorectal cancer (CRC)." (PMID 38432629, 2024). "In 2010, researchers found that in colorectal cancer, FOXQ1 promoted tumorigenicity and tumor growth by upregulating p21 expression, which in turn enhanced angiogenesis and anti-apoptosis." (PMID 33098639, 2020). "In colorectal cancer, FOXQ1 not only promoted metastatic potential but also enhanced tumorigenicity and tumor growth." (PMID 32592372, 2020). "Studies have indicated that FOXQ1 is also an oncogene in multiple tumors, including colorectal cancer (CRC), non-small cell lung cancer, breast cancer, ovarian cancer, bladder carcinoma, stomach cancer, liver cancer, and neuroglioma." (PMID 33330033, 2020). "Correlation between FOXQ1 expression and clinicopathological characteristics of colorectal cancers (CRCs) in cohort of human CRC tissues." (PMID 33330033, 2020). "In colorectal cancer, miR-320, miR-342 and miR-106a restrained tumor cell growth by targeting FOXQ1." (PMID 33098639, 2020). "It has been documented that both FOXM1 and FOXQ1 serve as two targets of miR-342-3p in colorectal cancer." (PMID 30678643, 2019). "Both FOXM1 and FOXQ1 mediate the tumor-suppressive activity of miR-342-3p in colorectal cancer cells." (PMID 30678643, 2019). "MiR-342 was shown to be a negative regulator of E2F1 affecting MYC expression in lung cancer cells and also negatively regulate FOXM1 and FOXQ1 expression in colorectal cancer cells." (PMID 29599914, 2018). "By contrast, FOXQ1 promotes the progression and metastasis of esophageal cancer, breast cancer, pancreatic cancer, and colorectal cancer." (PMID 30360388, 2018). "Recent several studies reported that Foxq1 was markedly overexpressed in colorectal cancer and glioma, which enhanced tumorigenicity and tumor growth in vivo." (PMID 25098939, 2014). "Recent studies have been reported that FoxQ1 is markedly overexpressed in colorectal cancer and enhances tumorigenicity and tumor growth in vivo." (PMID 23383267, 2013). "The forkhead box transcription factor FOXQ1 has been shown to be upregulated in colorectal cancer (CRC) and metastatic breast cancer and involved in tumor development, epithelial-mesenchymal transition and chemoresistance." (PMID 23555880, 2013). "FOXQ1 is also overexpressed in colorectal cancer where it increases tumorigenicity by its angiogenic and antiapoptotic effects." (PMID 23213280, 2012).
colorectal cancer (continued). "Instead, we observed that FOXQ1 differentially regulates the expression of major Wnt pathway target genes, and synergises with Wnt signalling in imposing an EMT-associated transcriptional program on colorectal cancer cells." (PMID 39777582, 2025). "FOXQ1 promotes PI3K/AKT activity in colorectal cancer, and the abundant expression of FOXQ1 in FLC suggests that a similar mechanism may exist." (PMID 35482409, 2022). "Research suggests that FOXQ1 is closely related to the occurrence of different cancers and could accelerate the migration of esophageal, gastric, and colorectal cancer cells." (PMID 36118871, 2022). "RP9P promotes colorectal cancer progression by regulating the miR-133a-3p/FOXQ1 axis." (PMID 35600345, 2022). "FOXQ1 functions as an oncogene in colorectal carcinoma, gastric cancer, and NPC." (PMID 30678643, 2019). "FOXQ1 facilitated metastasis in colorectal carcinoma cells which had undergone TGF-β-induced EMT." (PMID 29050292, 2017). "Moreover, FOXQ1 promoted invasion and metastasis in colorectal cancer cells that had undergone EMT induced by TGF-β." (PMID 27223064, 2016). "Foxq1 has recently been shown to be one of the most highly expressed genes in human colorectal cancer and has been shown to be a direct target of Wnt signaling, which is often constitutively activated in colorectal cancer cells." (PMID 25165462, 2014). "Our findings suggest that FoxQ1 could be a critical pathway in glioma tumorigenesis, which is supported by a recent report showing that FoxQ1 is overexpressed in colorectal cancer." (PMID 23383267, 2013). "Interestingly, interrogation of the expression of this identified gene panel (SOX4, FOXM1, and FOXQ1) in The Cancer Genome Atlas (TCGA) Colorectal cancer data set revealed significantly shorter disease-free survival in patients with elevated expression of these genes (Logrank Test P-Value: 0.00581)." (PMID 27119506, 2016). "Interestingly, interrogation of the expression levels of this gene panel (SOX4, FOXM1, and FOXQ1) in The Cancer Genome Atlas (TCGA) colorectal cancer data set (319 patients) revealed significantly poor disease-free survival in patients with elevated expression of this gene panel (P-Value: 0.0058)." (PMID 27119506, 2016). "In colorectal cancer, the lncRNA, LINC00543, blocks maturation of miR-506-3p, resulting in elevated FOXQ1 and subsequently CCL2, which recruits macrophages and skews macrophages toward the M2 phenotype." (PMID 41154428, 2025). "Consistent with this notion, depletion of FOXQ1 inhibited the TGF-β-dependent EMT of mouse mammary epithelial cells and the invasion of colorectal cancer cells into Matrigel substrate." (PMID 39777582, 2025). "In colorectal cancer (CRC), TAMs induce EMT program to enhance CRC migration, invasion, and CTC-mediated metastasis by regulating the JAK2/STAT3/miR-506-3p/FoxQ1 axis, which in turn leads to the production of CCL2 that promote macrophage recruitment." (PMID 36817086, 2023). "FOXQ1, a member of the FOX family, is overexpressed in colorectal cancer, and it enhances tumorigenicity and tumor growth." (PMID 34103026, 2021). "Correlation analysis of FOXQ1 and Twist1, CCL2, or CD31 expression in cohort (n=83) colorectal cancer (CRC) tissues." (PMID 33330033, 2020). "Forkhead box Q1 (FOXQ1) is a well-established oncogene in multiple tumors, including colorectal cancer (CRC); however, whether FOXQ1 contributes to angiogenesis and TME modification in CRC remains largely uncharacterized." (PMID 33330033, 2020). "Like FOXQ1, KRT23 has been connected with cancer progression in colorectal cancer." (PMID 31404997, 2019). "The role of FOXQ1 in immunology has been preliminarily confirmed, with previous research showing that cancer-related macrophages induce epithelial–mesenchymal transition by regulating the JAK2/STAT3/miR-506-3p/FOXQ1 axis, thereby enhancing the invasion and migration of colorectal cancer cells." (PMID 36118871, 2022).
colorectal cancer (continued). "For example, miR-342 may suppress the expression levels of FOXM1 and FOXQ1 through direct binding within the putative 3’-UTR binding sites of these genes, thereby inhibiting the proliferation, migration, and invasion of colorectal cancer cells in a xenograft animal model." (PMID 30360388, 2018).
nasopharyngeal carcinoma (23 papers, 2014 to 2025). A carcinoma arising from the nasopharyngeal epithelium. "On the other hand, Luo and colleagues observed that FOXQ1 enhances the vascular mimicry of nasopharyngeal cancer cells." (PMID 39777582, 2025). "circCRIM1 was observed to be upregulated in NPC cells and by sponging miR-422a alleviated the inhibitory effect on FOXQ1 in nasopharyngeal carcinoma." (PMID 40176914, 2025). "Other studies show that miR-506 functions as an oncosuppressive microRNA in nasopharyngeal carcinoma, exerting its tumor-suppressing activity primarily by suppressing Forkhead box protein Q1 (FOXQ1) expression." (PMID 40248198, 2025). "LINC00667 up-regulates FOXQ1 by combining with miR-4319 in a competitive manner, hence facilitating the malignant phenotype of nasopharyngeal carcinoma cells." (PMID 37827696, 2023). "For example, circCRIM1 acts as a ceRNA for the miR-422a-FOXQ1 axis, ultimately leading to nasopharyngeal carcinoma metastasis, EMT, and docetaxel chemotherapy resistance." (PMID 35817771, 2022). "CircRNA CRIM1 was reported to promote nasopharyngeal carcinoma DTX chemoresistance through upregulating FOXQ1." (PMID 35659274, 2022). "A recent study showed that circCRIM1 prevented its inhibitory effect on the target gene FOXQ1 through competitive binding with miR-422a, promoted the metastasis of nasopharyngeal carcinoma, and developed resistance to docetaxel chemotherapy." (PMID 34603369, 2021). "For example, circCRIM1 upregulating FOXQ1 to promote metastasis and docetaxel chemoresistance of nasopharyngeal carcinoma." (PMID 34172072, 2021). "Investigators have discovered that miR-124, miR-506 and miR-342-3p suppressed nasopharyngeal carcinoma cell proliferation and metastasis by targeting FOXQ1." (PMID 33098639, 2020). "Hence, circCRIM1, functioning as a ceRNA, sponges miR-422a to alleviate its inhibitory effects on FOXQ1 in nasopharyngeal carcinoma, promoting metastasis and chemoresistance." (PMID 40176914, 2025). "In vivo, Foxq1 promoted the growth and metastasis of nasopharyngeal carcinoma, which could be prevented by EGFR inhibitors." (PMID 33875643, 2021). "Literature search has revealed different targets of miR-124 in different tissues and tumor types, such as Foxq1 in nasopharyngeal cancer, CCAAT/enhancer-binding protein-α in macrophages, PTBP1 in neuronal differentiation, and CAV1 and FLOT1 in renal clear cell carcinoma." (PMID 28212569, 2017). "Hong and colleagues proved that circCRIM1 was upregulated in nasopharyngeal carcinoma (NPC) and promoted NPC chemoresistance via upregulating FOXQ1." (PMID 36624091, 2023). "CircCRIM1 has been reported to promote nasopharyngeal carcinoma (NPC) metastasis and docetaxel chemoresistance via serving as a ceRNA against miR-422a to improve the FOXQ1 level." (PMID 36845400, 2023). "FOXQ1 promotes EGFR expression at mRNA and protein levels, mediates the EGFR signaling activity, and increases the metastasis of nasopharyngeal carcinoma (NPC) by inducing vasculogenic mimicry." (PMID 41347087, 2025).
hepatocellular carcinoma (18 papers, 2014 to 2025). A malignant tumor that arises from hepatocytes. "In general, high FOXQ1 expression appears to be associated with a poor clinical outcome, and has been identified as an independent prognostic marker for worse survival in colorectal, pancreatic, lung, gastric, and hepatocellular carcinomas (HCC)." (PMID 39777582, 2025). "al. revealed that miR-4319-mediated inhibition of FOXQ1 repressed the epithelial-mesenchymal transition and prevented cancer stemness of hepatocellular carcinoma." (PMID 35183223, 2022). "In hepatocellular Carcinoma, FoxQ1 expression promotes macrophage infiltration through the VersicanV1/CCL2 axis." (PMID 32653013, 2020). "Another study reported that FoxQ1 promotes hepatocellular carcinoma metastasis through provoking EMT by transactivating ZEB2 and VersicanV1 expression." (PMID 25356753, 2014). "Overexpression of FOXQ1 attenuated the antitumor effect of sorafenib on hepatocellular carcinoma." (PMID 38839744, 2024). "Since sorafenib-induced ferroptosis plays an important role in the treatment of hepatocellular carcinoma, we explored whether FOXQ1 affects the therapeutic sensitivity of sorafenib by regulating ferroptosis." (PMID 38839744, 2024). "Interestingly, in a recent study hepatocellular carcinoma cells expressing FoxQ1 were shown to increase recruitment of macrophages through CCL2 production." (PMID 29203829, 2017). "FOXQ1 is also overexpressed in hepatocellular carcinoma and induces metastasis." (PMID 26022688, 2015). "Foxq1 was a prognostic marker for patients in gastric cancer and hepatocellular carcinoma." (PMID 25098939, 2014). "The upregulation of FOXQ1 seems to be consistent with previous studies suggesting an AHR-dependent increase in the expression of this transcription factor either in rat hepatic progenitor cells or in a rat hepatoma cell line exposed to PCB126 and TCDD, respectively." (PMID 32610656, 2020). "As shown in the previous study, SOX12, a direct target of FOXQ1, promotes hepatocellular carcinoma (HCC) metastasis by upregulating Twist1 and FGFBP116." (PMID 30858360, 2019). "The high expression of FOXQ1 in hepatocellular carcinoma (HCC) cells may be related to its biological function as a therapeutic target for HCC." (PMID 41347087, 2025). "For example, miR-4319-mediated FOXQ1 inhibition suppressed EMT and prevented cancer stemness in hepatocellular carcinoma." (PMID 37875474, 2023). "A recent research on the microenvironment development of hepatocellular carcinoma (HCC) illustrated NDRG1 increase in HCC tissues, which cooperated with FOXQ1 to promote hepatic stellate cells recruitment." (PMID 34965023, 2021). "It was reported that the miR-4319, as a cancer related miRNA, could induce inhibition of EMT and prevente cancer stemness of hepatocellular carcinoma (HCC) through targeting FOXQ1." (PMID 34391433, 2021). "In hepatocellular carcinoma, ZEB2 was shown to be essential for FOXQ1-dependent tumour metastasis." (PMID 39777582, 2025). "In this study, although FOXQ1 expression was not significantly changed under short-term sorafenib stimulation, it was significantly increased in cells with long-term stimulation and tolerance to sorafenib, which affected the sensitivity of hepatocellular carcinoma cells to sorafenib." (PMID 38839744, 2024). "In addition, CAFs induce forkhead box Q1 (FOXQ1) expression; as a result, N-myc downstream-regulated gene 1 (NDRG1) is trans-activated to enhance hepatocellular carcinoma (HCC) initiation." (PMID 30380628, 2018).